SUMO2 (small ubiquitin like modifier 2)
Diseases named in the same sentence as SUMO2 in open-access papers (continued):
Sharing a sentence is not in itself a finding about the gene and the disease.
soft tissue tumors (1 paper, 2025). "Taken together, our study identifies SUMO2 as a novel, selective vulnerability in synovial sarcoma, suggesting new avenues for targeted treatment of soft tissue tumors." (PMID 40804185, 2025). "This multi-screen study identifies SUMO2 as a critical regulator of the SS18::SSX fusion oncogene, suggesting a novel vulnerability for these soft tissue tumors." (PMID 40804185, 2025).
synovial sarcoma (1 paper, 2025). "The effectiveness of SUMO2 inhibition in synovial sarcoma models by specifically suppressing the pathogenic features of the SS18::SSX fusion oncoprotein indicate that SUMO2 is a highly selective vulnerability in synovial sarcoma as indicated by our analysis of the Dependency Maps (DepMap) data." (PMID 40804185, 2025). "Taken together, our results reveal SUMO2 inhibition as an attractive therapeutic strategy in synovial sarcoma." (PMID 40804185, 2025). "Taken together, our results highlight the potential of SUMO2 inhibitors as promising therapeutic targets for SySa, with TAK-981 emerging as a particularly strong candidate for clinical testing in patients with synovial sarcoma." (PMID 40804185, 2025).
type 2 diabetes (1 paper, 2025). "Interestingly, the human type 2 diabetes risk gene SUMO2, which is specifically associated with alpha cell heterogeneity, was earlier linked to mitochondrial dysfunction in beta cells." (PMID 39508880, 2025). "Therefore, alterations of Sumo2 in alpha cells could affect alpha cell glucagon secretion via similar mechanisms and promote type 2 diabetes pathogenesis." (PMID 39508880, 2025).
infection (30 papers, 2011 to 2025). The state of being infected such as from the introduction of a foreign agent such as serum, vaccine, antigenic substance or organism. "Infection of HA-HisSUMO2 cells with wt HSV-1 caused a reduction in the overall abundance of His-SUMO2 conjugated proteins, which was more marked at later times of infection." (PMID 26200910, 2015). "Interestingly, chromatin occupancy by SUMO2/3 may finely tune viral latency or reactivation, or control the expression of host immune-related genes during infection by Kaposi’s sarcoma associated herpes virus." (PMID 35181598, 2022). "Subsequently, at 30 min, the expression levels for all the analyzed genes involved in SUMOylation were upregulated (except for SUMO2), and the same phenomenon was observed 4 h after the infection." (PMID 37165081, 2023). "Infections often stimulate proteasomal activity resulting in the increased turnover of sumoylated proteins, especially those that are conjugated with SUMO2/3." (PMID 35181598, 2022). "A significant upregulation of the expression profile of SUMOylated proteins by both SUMO-1 and SUMO-2/3 was observed at 48 h post-infection." (PMID 35734580, 2022). "Overexpression of SUMO1 or SUMO2 in cultured HeLa cells significantly reduces infection by L. monocytogenes." (PMID 35181598, 2022). "This experiment revealed that SUMO2/3-modified proteins increased 2 h post-infection and decreased later." (PMID 29352251, 2018). "In this study, we show that Shigella induces a massive decrease in SUMO1 and SUMO2/3 conjugates at late time post-infection in epithelial cells in culture and in the intestinal mucosa." (PMID 29231810, 2017). "The results demonstrated that the expressions of SUMO1, SUMO2 and Ubc9 were significantly inhibited at 12 h, 24 h and 36 h post infection, which correlated with robust expression of viral protein VP7 reflecting GCRV replication." (PMID 29069722, 2017). "To investigate the impact of Shigella infection on global sumoylation of host cell proteins, we followed the global pattern of proteins conjugated to SUMO1 and SUMO2/3 at timed intervals after infection (0 to 180 min)." (PMID 29231810, 2017). "Sustained expression of the ectopic miRNA-resistant RNF4 during productive infection was accompanied by failure to accumulate high molecular weight SUMO2/3 conjugates." (PMID 28414785, 2017). "In this study we set out to characterize changes to the cellular SUMO2 proteome in response to infection with wild type (wt) HSV-1 using Mass Spectrometry (MS)-based quantitative proteomics." (PMID 26200910, 2015). "Infection of control cells resulted in a significant localization of SUMO-1 and SUMO-2/3 conjugates, as well as PML, to sites closely associated with viral genomes (shNeg panels)." (PMID 21949651, 2011). "High-content screening analysis showed that in SUMO1-KO cells, SARS-CoV-2 exhibited single-cell infection with a higher infection rate, whereas clustered infection and increased cell fusion were observed in SUMO2-KO cells compared to wild-type (WT) A549-hACE2 cells." (PMID 40521184, 2025). "In contrast, pre-infection with PIV5 did not provide substantial protection against IAV-induced loss of SUMO2/3-modified TRIM28." (PMID 40920817, 2025). "The ability of PIV2, but not PIV5, pre-infection to limit IAV-induced loss of SUMO2/3-modified TRIM28 correlates well with our observation that PIV2-V, but not PIV5-V, efficiently engages with TRIM28." (PMID 40920817, 2025). "Interestingly, at 60 min post-infection, a significant elevation of ROS generation was observed upon knockdown of SUMO-2/3 and UBC9 by ~2-fold, SUMO-1 by ~3-fold, AOS-1 by ~4-fold, and UBA2 by ~6-fold compared to MOCK." (PMID 35734580, 2022). "Moreover, the clinical S. aureus NSA739 strain, but not the coagulase negative S. epidermidis strain, reduces specifically and significantly SUMO1 and SUMO2/3-conjugates 24 h post-infection." (PMID 34360873, 2021).
infection (continued). "SUMO1 and SUMO2/3 conjugates decreased in a multiplicity-of-infection-dependent manner." (PMID 29231810, 2017). "Analysis of our TAP-SUMO-enriched mass spectrometry data using a stringent 1% false discovery threshold and our slice-by-slice bioinformatic strategy revealed that only NS1, M1, and NEP satisfied our filtering criteria for SUMO1- and SUMO2-modified targets during infection." (PMID 26549460, 2015). "The use of SILAC Light, Heavy and Medium media for HSV-1 infected and uninfected HA-HisSUMO2 cells and uninfected control HA-His only cells, respectively, allowed for the relative fold changes to be calculated for His-SUMO2 purified proteins and unmodified proteins following infection." (PMID 26200910, 2015). "In addition, ICP0 also induces the widespread degradation of SUMO-1 and SUMO-2/3 conjugate proteins during infection." (PMID 21949651, 2011). "Thus, for each virus, we conducted 2 independent “label-swap” stable isotope labeling by amino acids in cell culture (SILAC) experiments using an A549 cell line stably expressing N-terminal tandem-affinity purification (TAP)-tagged SUMO2 to determine the impact of infection on the SUMO subproteome." (PMID 31391303, 2019). "The few instances of APH0032-SUMO2/3 colocalization that were inconsistently observed for some ApVs may be simply due to the fact that SUMO2/3-modified proteins pronouncedly label the AVM throughout infection." (PMID 27713867, 2016). "After 24 h of infection, the expression levels of UBE2C and PSMD6 the expression levels returned to unstimulated baseline levels, while SUMO1, SUMO2 and PSMC1 showed slightly higher expression levels than uninfected control cells." (PMID 37165081, 2023). "The results confirmed the significant upregulation of a minimum of 1.5-fold in the expression levels of SUMO-2/3, SUMO-activating E1 enzymes (AOS-1), and SUMO conjugating E2 enzyme (UBC9) at 48 h post-infection compared to uninfected macrophages." (PMID 35734580, 2022). "These and numerous other studies therefore indicate that modification by SUMO1 and SUMO2/3 may have distinct physiological outcomes, the latter particularly emerging as a crucial mediator of cellular and organismal responses to physiological or environmental stress conditions, including infection." (PMID 35181598, 2022). "It was recently reported that during infection, SUMO-1 localizes outside RCs, whereas SUMO-2 and SUMO-3 are mainly detected inside RCs." (PMID 32184235, 2020). "In contrast to the wild-type strain, infection with an isogenic avirulent capsule mutant (strain 52145 ΔwcaK2) induced an increase in SUMO1- and SUMO2/3-conjugated proteins." (PMID 32994335, 2020). "The SUMO2 concentration began dropping approximately 2 h after HSV-1 infection and continued to decrease up to 9 h after infection." (PMID 29114028, 2017). "It was next examined if infection results in a corresponding increase in expression of SUMO-1 and SUMO-2/3." (PMID 29056733, 2016). "Depletion of the SUMO isoforms did not affect the efficiency of wt HSV-1 gene expression during high multiplicity infections and the remaining SUMO1 and SUMO2/3 proteins in these cells were sensitive to HSV-1 mediated reductions." (PMID 26200910, 2015). "Infection of HeLa cells with L. monocytogenes results in a general decrease in overall SUMO1 and SUMO2/3 conjugates." (PMID 23795346, 2012). "The results showed that post-infection, SUMO2/3 partially co-localized with LaminB1, but not with RanGAP1 and RanBP2." (PMID 40521184, 2025). "To gain precise insights into the SUMOylation status of TRIM28 during infections with PIV2, PIV5 and IAV, we used a SUMO2/3-specific antibody to immunoprecipitate SUMO2/3-modified proteins from total cell lysates and assessed the SUMO2/3-modification status of TRIM28 by western blot." (PMID 40920817, 2025). "However, three months after infection, the JNPL3 mice expressing SUMO2 performed like the mice expressing GFP." (PMID 39000276, 2024).
infection (continued). "The co-expression of SUMO2 did not significantly improve the performance 1.5 months after infection." (PMID 39000276, 2024). "Knockdown of SUMO-1, SUMO-2/3, and UBC9 significantly elevated the ROS generation by ~2-fold, while UBA2 downregulation elevated ROS levels by ~3-fold compared to MOCK at 30 min post-infection." (PMID 35734580, 2022). "Though upon infection, knockdown of SUMO-2/3 also does not significantly modulate the expression of autophagy markers but regulates autophagy maturation, suggesting the direct or indirect role of target proteins SUMOylated by SUMO-2/3." (PMID 35734580, 2022). "Infection of PMA-differentiated THP-1 macrophages with L. donovani promastigotes significantly upregulated the expression levels of SUMO-1, SUMO-2/3, UBA2, and UBC9 by ≥2-fold, while a significant downregulation of SENP1 was observed at 48 h post-infection at the transcript level." (PMID 35734580, 2022). "Sloan and colleagues showed that infection of hepatocytes with HSV-1 results in reduced global cellular SUMOylation, which was particularly apparent at later times post infection (10 h) and also occurred in SUMO2-overexpressing cells." (PMID 33806893, 2021). "A549 epithelial cells showed a reduction in overall SUMO1-conjugated proteins of high molecular weight (>80 kDa) after 3 h of infection, with no changes in the overall SUMO2/3-conjugated proteins." (PMID 32994335, 2020). "Interestingly, when T84 cells were transfected with a precursor of miR-18, we observed a decrease in SUMO1- and SUMO2/3-conjugated protein levels with a more profound effect for SUMO2/3-conjugated proteins, as observed after LF82 infection." (PMID 30634511, 2019). "We found that three hours of L82 infection, unlike an infection with the non-pathogenic E. coli K12 MG1655 strain, induced a profound decrease in both SUMO1- and SUMO2/3-conjugated protein levels, compared with uninfected cells." (PMID 30634511, 2019). "Moreover, the authors found that three hours of LF82 infection were enough to induce a profound decrease in both SUMO1- and SUMO2/3-conjugated protein levels, compared with uninfected cells." (PMID 31726759, 2019). "In addition, we show that early post-infection, EMCV enhanced global SUMO2/3 modification, therefore it will be interestingly in future studies to identify cellular proteins conjugated to SUMO upon EMCV infection." (PMID 29352251, 2018). "Uninfected cells served as a control to examine if vimentin is modified by SUMO-2/3 in the absence of infection." (PMID 29056733, 2016). "The SUMO2-mediated degradation of USP7 observed under the ectopic expression of EBNA1 in HEK293 cells, but not when LCL cells express endogenous levels of EBNA1, suggesting that USP7 could be a key balance molecule to establish latency from primary infection." (PMID 32176739, 2020). "Although EMCV modulated global SUMO2/3 modification, its effect on PKR 2 h and 4 h post-infection seems to be specific since EMCV did not alter the modification of STAT1 that was shown previously to be SUMOylated7,23." (PMID 29352251, 2018).
cancer (27 papers, 2013 to 2026). A tumor composed of atypical neoplastic, often pleomorphic cells that invade other tissues. "Given the reports that SUMO2 and SUMO2 conjugated proteins are identified in exosomes, SUMO2 and its target proteins can serve as a circulating biomarkers for determining cancer risk and for evaluating the chemotherapy response." (PMID 34715855, 2021). "Our findings showed a notable decrease in SUMO2 staining within the nucleus of the residual cancer tissues after treatment." (PMID 38890737, 2024). "This is in contrast with earlier studies in cancer cells where DBC1 was found primarily SUMOylated by SUMO2/3 during etoposide-induced DNA damage." (PMID 37683133, 2023). "Normal cells are also expected to recruit SUMO2 substrates for mitotic events, but the required levels are lower than cancer cells." (PMID 36980166, 2023). "In summary, SUMO2 is identified as the master regulator of the processes involved in generating cancer hallmarks; hence it is a promising anti-GBM drug target." (PMID 34715855, 2021). "In the liver samples, we observed that the immunoreactivity of SUMO2/3 or p65 was higher in the para-carcinoma than that in the carcinoma." (PMID 26458400, 2015). "Elevated levels of SUMO1 and SUMO2/3 conjugates in RMS cell lines, compared to normal human skeletal muscle cells, underscore the association between upregulated SUMOylation and aggressive cancer phenotypes." (PMID 40549307, 2025). "SUMO2 has also been confirmed to be majorly upregulated in various other cancer cell lines." (PMID 34715855, 2021). "The discovery of the intersection between SUMO1 and SUMO2 modification switch of both STUB1 and KAP1 sheds new light on the regulation of EBV latency and lytic replication, which provides a potential therapeutic target against EBV-associated cancers." (PMID 32176739, 2020). "Our findings provide a new explanation for the enrichment of Sp1 protein in cancers and suggest a global regulation of SUMO2/3 conjugated proteins whose levels may be tightly controlled by SENP3 and RNF4." (PMID 26511642, 2016). "We found that the genes targeted by SUMO-2/3 after viral reactivation are significantly involved in several pathways related to cellular immune responses, cytokine signaling, cell growth, apoptosis and cancer." (PMID 24267727, 2013). "Besides, pro-tumourigenic cancer stem cells, the tumour-promoting aberrant immune cells such as microglia and monocyte-derived macrophages, were also identified to express high levels of SUMO2." (PMID 34715855, 2021). "To gain further insights into the molecular mechanisms and to explain the general suppression of MHC-I in cancers with activated SUMOylation, we depleted SUMO1 and SUMO2/3 with specific siRNAs." (PMID 35499080, 2022). "With regard to MYC-dependent cancers, we found a strong SENP6-dependent increase of SUMO2/3 conjugates, revealing that SUMO conjugation is activated either by induction of the SUMO conjugation machinery or by loss of the cellular safeguard deSUMOylase SENP6." (PMID 35022408, 2022). "Moreover, our data indicate a requirement for enhanced SUMO2/3 equilibrium in rapidly proliferating cultured cells, which suggests that a high availability and degree of conjugation of SUMO2/3 may occur in, and in turn facilitate, proliferating cancer cells." (PMID 29942033, 2018). "Strikingly, SS was the most sensitive subtype of cancer to knocking down UBE2I (UBC9), SUMO2 (the most widely expressed SUMO in humans), PIAS1, SAE1 and UBA2 (SAE2), molecules encompassing the entire SUMOylation process and pointing to a selective dependency of SS on this PTM." (PMID 38883782, 2024).
cancer (continued). "For this reason, SUMO2, SUMO3 and SUMO4 can be potentially exploited in further anti-cancer mechanisms investigations (p-value = 0.024 in the present study), in order to shed light on the regulatory mechanisms underlying the activity of SUMO machinery in an oncogenic framework." (PMID 35741808, 2022). "Thus, PML orchestrates mESC state by coordinating SUMO2-conjugation of different transcriptional regulators, raising new hypotheses about PML roles in cancer." (PMID 36175410, 2022). "Additionally, combining SUMO2 inhibitors with FDA approved drugs and other anti-cancer phyto-compounds may efficiently target GBMs through drug synergism and may combat treatment resistance." (PMID 34715855, 2021). "APP and SUMO2, which play an important role in protein homeostasis with reported involvement in cancer, and MAPK1, a kinase that regulates cell cycle and is well-known for its roles in cancers, were among the top 10 genes exhibiting the highest frequencies in PIE-MINs of at least two cancer types." (PMID 28765560, 2017). "In the HepG2 cancer-cell line, we did not detect the over-90 kDa conjugated form of SUMO2/3." (PMID 27486970, 2016). "To explore drugs that may act against KSHV and related cancer cells through targeting LANASIM, we developed a luciferase based live-cell reporter assay (containing two subunits of SmBiT and LgBiT) to quantitatively measure the interaction of LANASIM with SUMO2 via NanoLuc Binary Technology." (PMID 31830143, 2019).